HIF1A (hypoxia inducible factor 1 subunit alpha)
Diseases named in the same sentence as HIF1A in open-access papers (continued):
Sharing a sentence is not in itself a finding about the gene and the disease.
colon carcinoma (continued). "Therefore, HIF-1α/MDR1 may be a promising target in the colon cancer treatment, and the reversal of colon cancer MDR can be achieved when HIF-1α/MDR1 expression is specifically inhibited." (PMID 24901645, 2014). "In the current study, we showed that while 15-LOX-1 decreased HIF-1α mRNA expression to variable degrees and to biologically nonsignificant levels (<30%) in two of three tested cell lines, it consistently decreased protein expression in all tested colon cancer cell lines." (PMID 24634093, 2014). "However, 30 colon cancer cases (44%) showed high HIF-1α expression." (PMID 20953377, 2010). "Transfection of colon cancer cells with si-P4HA2#1 and CHX treatment revealed that HIF-1α stability decreased in the P4HA2 knockdown group." (PMID 39920992, 2025). "Western blot analysis showed that hypoxia promotes the stability of HIF‐1α, while overexpression of PKN2 significantly downregulated the expression and nuclear internalization of HIF‐1α in colon cancer cells." (PMID 40515512, 2025). "HB7, HB9, and HB10 demonstrated the highest transcriptional levels of HIF-1α and HIF-2α, approximating a 5-fold increase compared to the levels observed in SW48 colon cancer cells, which served as a control." (PMID 40427061, 2025). "Mechanistically, KynA downregulates the expression of P4HA2 to promote the ubiquitination and degradation of HIF-1α, which leads to a decrease in the transcription of HILPDA, and ultimately leads to an increase in lipolysis of colon cancer cells." (PMID 39920992, 2025). "In conclusion, quercetin inhibited the invasion and migration of advanced metastatic colon cancer LOVO cells under hypoxia through inhibition of ROS and HIF-1α expression and the downregulation of PI3K/AKT pathway." (PMID 41550172, 2024). "Tumor microenvironment is often in a state of hypoxia in the body, and hypoxia can increase the expression of HIF-1α and induce EMT in colon cancer cells." (PMID 41550172, 2024). "In colon cancer, under hypoxic conditions, CAF-derived IL-6 activates STAT3 signaling to promote tumor progression or induce drug resistance via a HIF-1a/miR-338-5p/IL-6 feedback loop." (PMID 39251966, 2024). "Many miRNAs can directly act on VEGF or inhibit angiogenesis through other pathways (e.g., HIF-1α, PI3K/AKT, etc.), while some miRNAs, specifically many exosomal (exo)miRNAs, are capable of promoting colon cancer angiogenesis." (PMID 39062921, 2024). "The results revealed quercetin effectively inhibited the invasion and migration of high metastatic advanced colon cancer LOVO cells under hypoxia through the inhibition of ROS and the expression of HIF-1α and PI3K/AKT pathway." (PMID 41550172, 2024). "To further investigate the effect of HIF-1α on the migration and angiogenesis of CT26 colon cancer cells, we inhibited the HIF-1α pathway using a HIF-1α inhibitor (LW6)." (PMID 37239383, 2023). "Recently, it was demonstrated that CQ promotes colon cancer cells to become more sensitive to 5-FU via inhibiting ataxia telangiectasia and Rad3-related (ATR) kinase-mediated HIF-1α translation and interfering with HIF-1α’s hypoxic function." (PMID 37569598, 2023). "One study found that inhibition of Nrf2 blocked the accumulation of HIF-1α in colon cancer cells under hypoxic conditions and inhibited the expression of VEGF and HIF-1α target genes while reducing the growth and angiogenesis of xenograft tumors in mice." (PMID 37359553, 2023).
colon carcinoma (continued). "For example, the exposition of mouse colon cancer ES cells to 1% oxygen for 24 h showed an upregulation of HIF-1α and MMP-2 that decreased with the use of HIF-1α siRNA or in knockout HIF-1α−/− cells cultured in normoxic conditions." (PMID 38069210, 2023). "For example, a novel HIF-1α inhibitor, IDF-11774, blocking HIF-1α accumulation under hypoxia in human colon cancer cells has been found to suppress tumor growth by inhibiting the expression of GLUT1 and PDK1." (PMID 36551540, 2022). "The same research group also validated TRPC5 role in mediating HIF-1α response in tumour progression in colon cancer, where TRPC5 activated the HIF-1α-Twist signalling pathway to promote EMT, migration and proliferation in SW620 colon cancer cells." (PMID 35806388, 2022). "Not only this, Imamura and colleagues also explored the divergent role of HIF-1α and HIF-2α in SW480 colon cancer cells via the selective knockdown of the same isoforms." (PMID 35592530, 2022). "The HIF-1α-mediated PDK3 upregulation significantly inhibited cell apoptosis and increased resistance to either cisplatin or paclitaxel in colon cancer." (PMID 36551540, 2022). "Matrine has been found in studies to drastically suppress the expression of HIF-1α and its downstream regulatory targets of glucose metabolism GLUT1, HK2 and LDHA in colon cancer HCT116 and SW620 cells, reversing the Warburg Effect." (PMID 36339566, 2022). "Taking into consideration of the previous findings that HIF-1α is a vital element in tumor migration and invasion and much more important than HIF-2α in colon cancer." (PMID 35592530, 2022). "In colon cancer, EpICD was found to interact with β-catenin and hypoxia inducible factor 1α (HIF-1α) to promote the transcriptional activity of HIF-1α-targeted genes." (PMID 36369033, 2022). "In this current study, we supposed that miR-148a directly targets ROCK1 and c-Met to decrease angiogenesis and increase the apoptosis of colon cancer cells by inhibiting the secretion of VEGF and Mcl-1 through downregulation of HIF-1α under hypoxia." (PMID 35997665, 2022). "Exosomal miR-21-5p released by colon cancer cells inhibited VHL expression in Schwann cells, which in turn stabilized the HIF-1α protein and increased the transcription of NGF." (PMID 36522730, 2022). "Research on colon cancer suggested that the downregulation of NOS, COX-2, HIF-1α, VEGF, Ang-2, and Ang-4 was the result of SB treatment." (PMID 35784750, 2022). "In gastric cancer, IGF2BP3, an m6A reader, positively regulates HIF-1α gene and promotes angiogenesis through m6A regulation and can also regulate the VEGF gene to facilitate angiogenesis in colon cancer." (PMID 36246403, 2022). "Ginseng diol, a Chinese herbal component, also showed inhibition of HIF-1α formation and blocked the interaction between HIF-1α and STAT3, inhibiting the expression of PD-L1 in colon cancer cells, and also showed minor cytotoxicity in cell experiments." (PMID 36387147, 2022). "In colon tumors and HCT116 cells, HIF-1α recruits the ubiquitin ligase E3 parkin, forming a heterodimer that binds and ubiquitinates DICER, inducing its degradation by autophagosomes, thereby decreasing the expression of mir-200b." (PMID 35741024, 2022). "We also examined the expression of genes and transcription factors in key metabolic signaling pathways across the subpopulation, the most abundant genes in colon cancer were PDK1, NRF1, MYC, and HIF1A." (PMID 35755820, 2022). "In this study, we affirmed that miR-148a indirectly inhibited the expression of HIF-1α and Mcl-1 by directly binding to ROCK1 and c-Met, thereby enhancing apoptosis of colon cancer cells and decreasing angiogenesis in tissues containing such cells." (PMID 35997665, 2022). "Using human colon carcinoma HCT116 cells, esculetin was demonstrated to induce the hypoxia-inducible factor 1 alpha (HIF-1α), promote the secretion of vascular endothelial grown factor (VEGF), and inhibit HIF prolyl hydroxylases (PHD) activity." (PMID 33467396, 2021).
colon carcinoma (continued). "Depletion of HIF1α in NK cells disturbs angiogenesis and inhibits tumor growth in the MC38 (colon cancer) isograft mouse model." (PMID 34686682, 2021). "The combination of TAS-116 and palbociclib or abemaciclib markedly reduced the level of HIF1α and synergistically suppressed cell viability in SW480 colon cancer cells both in normoxia and hypoxia." (PMID 34686682, 2021). "For example, in colon cancer the hyper-activated WNT/β-catenin axis disrupts the interaction between XBP-1 and HIF-1α, attenuating the transcriptional activity of HIF-1α and decreasing the adaptation to hypoxia." (PMID 33423689, 2021). "For example, the adenomatous polyposis coli (APC) is a classic tumor suppressor, and it was repressed by HIF‐1α via a functional HRE on the its promoter in osteosarcoma and colon cancer cells." (PMID 33463054, 2021). "A previous report showed that HIF-1α promotes invasion by regulating the expression of MMP-2 and uPAR in HCT116 colon carcinoma cells." (PMID 32867190, 2020). "The positive correlation between CD68 and HIF1A, and the increased CA9 and LOX expression in CD68HighHIF1AHigh patients were validated on the Oncomine database (colon cancer Bittner cohort, with the highest number of patients)." (PMID 32231135, 2020). "Colon cancer cells were cultured in HSC-conditioned medium (CM), and HIF-1α expression and cell migration were analyzed." (PMID 32895059, 2020). "Analysis using the GEPIA dataset indicates that the YAP1 levels were positively correlated with TEAD1 in colon cancer, rectal cancer and CRC, and surprisingly, the YAP1 and TEAD1 levels were both positively correlated with HIF1A or LDHA." (PMID 33218358, 2020). "In an in vitro study using a cell-culture of human colon cancer cells, thalidomide inhibited the expression of both VEGF-A and hypoxia- inducible factor-1α (HIF-1α)." (PMID 32443710, 2020). "Since the CMS1–MSI-immune colon cancer subtype is also characterized by high MSI, high levels of BRAF mutations, and low levels KRAS mutations, we decided to explore whether CD68High tumors presented differences in HIF1A expression comparing MSI/MSS, and BRAF and KRAS wild-type versus mutated." (PMID 32231135, 2020). "In colon cancer cells treated with Yoda1, HIF-1α expression was significantly up-regulated, whereas HIF-1α expression was significantly inhibited after silencing Piezo1." (PMID 32152662, 2020). "For example, HIF-1α promoter is demethylated at CpG site within colon cancer, which promoting the binding of HIF-1α protein to its own promoter and thus affecting HIF-1α transcriptional activation and target genes activation." (PMID 33109235, 2020). "Even though it is well known that almost all cancer cells express HIF-1α and HIF-2α under hypoxic conditions, HIF-2α is essential in colon cancer growth and progression among HIFs." (PMID 32847073, 2020). "The Spearman analysis revealed a linear positive correlation between HIF-1α and MDR1 expression (p < 0.001; R ≥ 0.8) in the blood of breast, ovarian, prostate and colon cancer." (PMID 30746305, 2019). "The aim of this study was to examine the relation of MVD to disease-recurrence, in both stage II and stage III colon cancer patients, while taking into account the amount of tumour stroma (TSP) and expression of HIF1A and VEGFA." (PMID 31420015, 2019). "We examined the effects of stable knockdown of HIF-1α or HIF-2α expression on autophagy and drug resistance in colon cancer cells." (PMID 31151160, 2019). "Correlation of HIF-1α, MDR1, and LAPTM4B expression with clinico-pathological features of colon cancer." (PMID 30746305, 2019). "In conclusion, our present study demonstrated that vanillic acid decreases HIF-1α protein synthesis by inhibiting mTOR/p70S6K/4E-BP1 and Raf/MEK/ERK pathways in human colon cancer HCT116 cells." (PMID 30678221, 2019).
colon carcinoma (continued). "In agreement with this notion, we have reported that HIF-1α and HIF-2α play opposing roles in canonical Wnt signaling activation in colon cancer cells despite both being essential for stemness and malignancy maintenance." (PMID 31151160, 2019). "It inhibits cancer cell angiogenesis through inhibiting HIF-1α and VEGF expression as well as the migration of human colon cancer cells." (PMID 30871059, 2019). "Our data showed that HIF-1α protein expression was significantly increased under normoxia and 1% O2 in PTBP3 OE colon cancer cell HCT116 and SW480." (PMID 31291975, 2019). "This study aimed to evaluate the prognostic value of MVD in stage II and III colon cancer and its relation to tumour-stroma-percentage (TSP) and expression of HIF1A and VEGFA." (PMID 31420015, 2019). "In the two colon cancer cell lines we tested, we found a detectable HIF-1α protein expression in normoxic condition (first lands), which suggested that there is residual HIF-1 activity in these colon cancer cells." (PMID 31849679, 2019). "There was 12–13 fold increased in expression of HIF-1α, two fold increased in MDR1 and 13–14 fold increased in LAPTM4B mRNA level in peripheral blood of breast, ovarian, prostate and colon cancer patients." (PMID 30746305, 2019). "Inhibition of HIF1α expression by Oroxylin A can decrease SREBP1 and FASN expression in the colon cancer cell line." (PMID 29588626, 2018). "Hypoxia can induce IL-11 expression in the human colon cancer cell line, HCT116, through cooperative interactions between HIF-1α and AP-1 within the IL-11 promoter." (PMID 30197757, 2018). "Overall, these data indicated that miR-675-5p, in colon carcinoma, is able to favour hypoxia induced EMT by sustaining HIF1α pathway." (PMID 28061476, 2017). "A previous study showed that OL downregulates HIF-1α in HT-29 colon cancer cells and NF-κB directly interacts with HIF-1α to regulate HIF-1α mRNA and protein levels." (PMID 28410190, 2017). "In fibroblasts, as well as breast and colon cancer cells, stimuli leading to PI3K activation increase HIF-1α protein levels through the downstream activation of Akt and mTOR." (PMID 28401064, 2017). "To study this further, we stained tissue sections of human colon tumors for the hypoxia markers CAIX and HIF1α and for the DNA damage marker phosphorylated histone 2AX (γH2AX)." (PMID 29156796, 2017). "In particular, miR-675-5p was found over expressed in metastatic colon cancer patients while, its silencing, induced in vitro the inhibition of the HIF1α guided EMT, indicating the miR-675-5p as a new putative target and predictive marker in colon cancer." (PMID 28061476, 2017). "We found that IDF-11774 reduced the HRE-luciferase activity of HIF-1α (IC50=3.65 μM) and blocked HIF-1α accumulation under hypoxic conditions in HCT116 human colon cancer cells." (PMID 28569777, 2017). "In a comprehensive study, these authors demonstrated that overexpression of NQO1 in RKO colon tumor xenografts led to significantly increased tumor growth rate and that knockdown of NQO1 inhibited growth but only in the context of functional HIF-1α." (PMID 28883796, 2017). "This study advances our knowledge of the activation mechanism of HIF-1α and indicates that ZFP91 plays an important, yet previously unappreciated, role in the tumorigenesis and progression of colon cancer." (PMID 27144516, 2016). "In primary colon tumors of patients, especially at advanced stages (UICC III/IV), a significantly higher gene expression of HIF1α (p<0.001) was observed." (PMID 27626684, 2016). "It has been shown that IGF-1 increases Hif1α synthesis through PI3K and MAPK pathways in colon cancer cells." (PMID 27148974, 2016).
colon carcinoma (continued). "For this purpose, endogenous PIN1 in human colon cancer (HCT116) cells was knocked down using PIN1 si-RNA, and stability of endogenous HIF-1α protein was monitored by a cycloheximide chase experiment." (PMID 26784107, 2016). "The human colon cancer specimens exhibited a robust expression of ZFP91 and HIF-1α compared with adjacent tissues." (PMID 27144516, 2016). "MIF is a known target of HIF1α, and we have shown recently that LPA induces HIF1α in colon cancer cells under normoxic conditions." (PMID 26352431, 2015). "Previously it was shown that the activation of Hif1α (which occurred in DAPIT cells) in embryonic stem cells and colon cancer cells under hypoxia inhibited transcriptional activity of β-catenin resulting in G1 arrest." (PMID 26161955, 2015). "Our previous study has shown that HIF-1α and MDR1/P-gp expression levels correlate in tumor tissues of colon carcinoma." (PMID 24901645, 2014). "Taken together, our results reveal complex roles for HIF-1α and HIF-2α in colon cancer cells, as has also been demonstrated in other cell types." (PMID 25396735, 2014). "We conducted this study to test the hypothesis that restoring 15-LOX-1 in colon cancer cells will inhibit cancer cells' hypoxia response of promoting metastasis and upregulating important events in the pathophysiology of metastasis (e.g., HIF-1α, angiogenesis, and tumor cell invasion and migration)." (PMID 24634093, 2014). "We found that 15-LOX-1 reexpression in colon cancer cells suppressed their survival, angiogenesis, cell migration and invasion, and VEGF and HIF-1α expression under hypoxia." (PMID 24634093, 2014). "The expression of HIF-1α and MDR1/P-gp can be used as a predictive marker for chemotherapy resistance in colon cancer." (PMID 24901645, 2014). "Correlation analysis demonstrated that the levels of FGF9 were positively correlated with those of HIF-1α (R = 0.758, P < 0.0001), suggesting that aberrant expression of FGF9 in colon cancer cells is induced by hypoxia." (PMID 24334956, 2014). "We suggest that the expression of HIF-1α and MDR1/P-gp can be used as a predictive marker for chemotherapy resistance in colon cancer." (PMID 24901645, 2014). "The expression of HIF-1α mRNA was detected in colon cancer cell lines, but the addition of PSK suppressed HIF-1α mRNA expression." (PMID 23181101, 2012). "In summary, we have demonstrated that HIF-1α, CXCR4, and VEGF are highly expressed in colon cancer samples as demonstrated using immunohistochemistry." (PMID 20953377, 2010). "Lastly, in order to quantify the message RNA of HIF-1α, CXCR4, and VEGF in colon cancer, the three marks expression at the mRNA levels were analyzed by real-time PCR." (PMID 20953377, 2010). "The results demonstrate that there is a statistically significant correlation between human colon cancer TNM stage and single HIF-1α, CXCR4, and VEGF expression levels." (PMID 20953377, 2010). "The differences in expression of the three molecules (HIF-1α, CXCR4, and VEGF) between benign hyperplastic polyps and colon cancer tissues were all found to be statistically significant (P < .05)." (PMID 20953377, 2010). "In this study, we demonstrate high expression of HIF-1α, CXCR4, and VEGF in human colon cancer specimens using immunohistochemistry." (PMID 20953377, 2010). "We further compared correlation of lymph node metastasis of colon cancer with combined high expression of both HIF-1α and CXCR4, of both HIF-1α and VEGF, or of both CXCR4 and VEGF." (PMID 20953377, 2010). "Furthermore, miR-148a represses HIF-1α/VEGF and Mcl-1 by directly targeting ROCK1/c-Met, thereby diminishing angiogenesis and enhancing apoptosis in colon cancer cells." (PMID 40305214, 2025). "In colon cancer, members of the miR-17–92 cluster activate Wnt/β-catenin signaling and epithelial-mesenchymal transition, while suppressing TGF-β signaling via direct targeting of TGFBR2, VEGFA and HIF1A." (PMID 41473312, 2025).